RBP4 (retinol binding protein 4)
Diseases named in the same sentence as RBP4 in open-access papers (continued):
Sharing a sentence is not in itself a finding about the gene and the disease.
Insulin resistance (continued). "Previous studies have found that a variety of hepatokines play an important role in the occurrence and development of insulin resistance and T2DM, including fibroblast growth factor 21 (FGF21), retinol binding protein 4 (RBP4), and fetuin A." (PMID 34858327, 2021). "RBP4-induced TLR4 expression activates the NLRP3 inflammasome in mice, which leads to the expression of inflammatory cytokines such as IL-1β, promotes insulin resistance and cardiac hypertrophy." (PMID 34638803, 2021). "Serum concentrations of RBP4 are increased in women with polycystic ovary syndrome (PCOS) and inadequately high concentrations of androgen and insulin resistance are characteristic of PCOS." (PMID 34068244, 2021). "Recent research indicates, indeed, that STRA6 is not only responsible for ROH intake but also, through the binding of RBP4 and ROH, can be involved in the onset of insulin resistance through the activation of the JAK/STAT pathway." (PMID 34945773, 2021). "Adipokines that stimulate insulin resistance include MCP‐1, RBP‐4, progranulin, chemerin, and ANGPTL2." (PMID 32440558, 2020). "Also, BAT released RBP4 may not be associated with insulin resistance given that cold-induced activation of BAT is associated with insulin sensitization." (PMID 32265845, 2020). "Thus, RBP4 may play a role in the development of insulin resistance in GDM." (PMID 31921323, 2020). "Another newly identified adipokine, Retinol-binding protein 4 (RBP-4), has emerged as a possible regulator of insulin resistance, obesity, and inflammation." (PMID 31803136, 2019). "The retinol-binding protein 4 (RBP4) has been postulated to play a role in glucose homeostasis, insulin resistance, and diabetes mellitus in human and animal studies." (PMID 30135138, 2018). "RBP4 and TTR levels, as well as homeostatic model assessment of insulin resistance (HOMA-IR) values, were significantly elevated among subjects with high triglyceride levels (p < 0.01, p < 0.05, p < 0.05, respectively)." (PMID 29747616, 2018). "The relative ratios of studied adipokines (e.g. resistin/RBP4, leptin/MCP-1 and MCP-1/RBP4) are correlated with fasting glucose and HbA1c levels as well as with insulin resistance/sensitivity and β-cell function indexes." (PMID 29785210, 2018). "There is evidence to suggest that RBP4 and TTR play a role in the development of insulin resistance and metabolic syndrome." (PMID 29747616, 2018). "RBP4 directly stimulates antigen-presenting cells, activating CD4+ T-helper cells, which trigger adipose tissue inflammation and, therefore, insulin resistance." (PMID 28286779, 2017). "Retinol binding protein 4 (RBP4) is an adipokine; its serum level is closely related to insulin resistance and T2DM." (PMID 27446956, 2016). "We analyzed the correlations of glucose tolerance and insulin resistance with the fasting levels of 10- and 12-(Z,E)-HODE/LA, RBP4, glycoalbumin, adiponectin, leptin, and hs-CRP." (PMID 26132231, 2015). "10- and 12-(Z,E)-HODE/LA, RBP4, hs-CRP, and adiponectin were significantly correlated with both glucose tolerance and insulin resistance." (PMID 26132231, 2015). "Lowering RBP4 levels through TTR inhibition was recently shown to be effective, improving insulin resistance and adipose tissue inflammation in obese mice." (PMID 25918733, 2015). "Another adipokine, circulating retinol-binding protein 4 (RBP4), directly contributes to insulin resistance and activates inflammatory pathways in macrophages, in part by increasing secretion of TNF-α and IL-6." (PMID 24303126, 2013). "The expression of RBP4 is inversely correlated with that of GLUT4 in adipocytes, and administration of recombinant RBP4 to normal mice induces insulin resistance." (PMID 23781214, 2013). "However, the associations between RBP4 levels and insulin resistance were not consistent." (PMID 24160775, 2013).
Insulin resistance (continued). "Furthermore, RBP4 level was increased in serum of lean and obese insulin-resistant humans compared to insulin-sensitive humans, indicating that higher RBP4 may reflect insulin-resistance independently of obesity." (PMID 23119072, 2012). "Presented is a unique top-down proteomic method for the analysis of Retinol Binding Protein 4 (RBP4), a clinically significant biomarker for the detection of insulin resistance and type 2 diabetes." (PMID 21479165, 2011). "Retinol binding protein 4 (RBP4), a 21-kDa protein synthesized in the liver and adipose tissue, has recently been described as an adipokine involved in the development of insulin resistance in mice and humans." (PMID 20932285, 2010). "Retinol-binding protein 4 (RBP4), leptin and resistin are adipocyte-derived biomarkers for insulin resistance and type 2 diabetes." (PMID 20633301, 2010). "In another study by Lee and colleagues, a DNA aptamer specific for retinol binding protein 4 (RBP4), a biomarker for insulin resistance and type II diabetes, was converted into an SPR biosensor after being functionalized onto a gold chip." (PMID 27873915, 2008). "Hence, this study aimed to measure RBP4, LCN2 and hsCRP levels in individuals with IFG, IGT, and newly diagnosed T2DM and to examine their relationship with insulin resistance and inflammation." (PMID 40951890, 2025). "In the biological pathway of insulin resistance, the elevated levels of MASP1, THBS1, GPLD1, AAT, HP, RBP4, ZAG, and ApoA-I may be positively correlated with each other, synergistically exacerbating insulin resistance." (PMID 40162315, 2025). "Overall, a correlation of RBP4 with insulin resistance in obesity and aging cannot be ruled out, but further larger studies are needed to focus on this subpopulation." (PMID 41227378, 2025). "Overexpression of RBP4 in the liver does not lead to insulin resistance, but in adipose tissue, it does." (PMID 38520616, 2024). "Studies have shown that elevated RBP4 levels in serum, in both humans and animals, may lead to the downregulation of GLUT4 in adipocytes, resulting in insulin resistance." (PMID 39518840, 2024). "A subsequent study demonstrated that RBP4 can activate antigen-presenting cells through the MyD 88-MAPK-NFκB pathway, leading to inflammatory infiltration in adipose tissue and inducing systemic insulin resistance." (PMID 38520616, 2024). "Moreover, serum retinol can bind to retinol-binding protein 4 (RBP4), and is delivered to adipose tissues, further stimulate macrophages bringing about increased local inflammation and systemic insulin resistance through a JNK-dependent pathway." (PMID 38306354, 2024). "Correspondingly, the serum RBP4 concentration is correlated with insulin resistance independent of BMI, and elevated serum RBP4 concentrations have also been detected in lean insulin-resistant patients, nonobese individuals, and normal-weight individuals." (PMID 38520616, 2024). "In addition, since RBP4 is mainly excreted through glomerular filtration, some studies have indicated that there may be no causal link between RBP4 and insulin resistance or T2DM and that the increased serum RBP4 levels in T2DM patients may be caused by reduced renal clearance efficiency." (PMID 38520616, 2024). "RBP-4 is correlated with the magnitude of insulin resistance independent of obesity, however, the effect of RBP-4 on bone metabolism is poorly understood." (PMID 36831180, 2023). "A previous study partly supported these findings, since circulating RBP4 positively correlated with triglyceride levels but not with BMI, fat mass and insulin resistance in healthy obese and non-obese individuals." (PMID 36837889, 2023). "Retinol binding protein-4 (RBP4) is a transport protein for retinol and a controversial organokine, which is also suggested to link obesity with its complications, particularly insulin resistance, T2DM, and MetS." (PMID 36835525, 2023).
Insulin resistance (continued). "While findings concerning maternal RBP4 in GDM and PE seem to vary, it is suggested that RBP4 could possibly be involved in the pathophysiology of late-onset PE by stimulating insulin resistance in obese mothers." (PMID 37239090, 2023). "In addition, they showed that the use of sitagliptin helped down-regulate retinol-binding protein-4 (RBP-4), a molecule that is known to be positively correlated with the severity of glucose intolerance and insulin resistance in women with previous GDM." (PMID 36077491, 2022). "RBP4 concentrations are not increased in children as they are in obese adults with long-standing severe insulin resistance and type 2 diabetes." (PMID 35634496, 2022). "RBP4 levels correlated positively with disease severity and insulin resistance in HS patients independent of BMI." (PMID 36499573, 2022). "They showed that RBP4 affects macrophages, dendritic cells, and CD4+ T-cells in adipose tissue, thereby promoting an inflammatory response, impairing insulin signaling and eventually leading to insulin resistance." (PMID 35334893, 2022). "Resistance exercise reduces circulating RBP4 levels without altering intramuscular adipocytes or insulin resistance, whereas neither anaerobic exercise nor controls reduce RBP4." (PMID 35309061, 2022). "Our findings implied that GCBE could improve body weight, organ weight, lipid profile, insulin resistance, HOMA-IR, adiponectin levels in serum, RBP4, and GLUT4 expression in adipose tissue of obese rats persuaded by HFD." (PMID 35629362, 2022). "This is the first study to report RBP4 and its elevation after HSCT as a marker of insulin resistance which may be the predominant manifestation of GvHD." (PMID 35977993, 2022). "The present data proved that GHR not only promoted the secretion of RBP4 from the liver by activating STAT5 but also maintained circulating RBP4 homeostasis and repressed renal clearance of RBP4 by provoking activation of the HIF1α/TTR axis, thus inducing systemic insulin resistance." (PMID 34373742, 2021). "RBP4 directly promoted basal lipolysis in adipocytes and also triggered adipose tissue inflammation by increasing adipose tissue macrophage and CD4 T cell infiltration, resulting in systemic insulin resistance." (PMID 34944728, 2021). "Additionally, RBP4 levels of the patients with IFG, insulin resistance or hyperinsulinemia were significantly higher than the patients without IFG, insulin resistance or hyperinsulinemia." (PMID 31956345, 2020). "Functional analyses have demonstrated that adipose tissues are capable of producing retinol binding protein 4 (RBP4)-positive exosomes to stimulate activated macrophages that secrete IL-6 or TNF-α in a TLR4-dependent manner, thus eventually inducing insulin resistance." (PMID 32878635, 2020). "RBP4 is not just a plasma carrier of retinol but also considered as a novel adipokine that plays an important role in insulin resistance." (PMID 31956345, 2020). "For example, a recent randomized and double-blind trial demonstrated that the DPPIV inhibitor sitagliptin attenuated insulin resistance and improved overall glycaemic control in women with GDM by a purported reduction in RBP4 (Retinol Binding Protein 4) levels." (PMID 31164969, 2019). "RBP4 acts as a negative acute phase inflammatory protein and contributes to systematic insulin resistance; it is upregulated in patients with obesity and T2DM." (PMID 30211220, 2018). "This trend fits with the theory of RBP-4 being a marker of obesity, rather than insulin resistance, as GHR−/− mice are obese but insulin sensitive." (PMID 28670222, 2017). "Similarly, retinol binding protein-4 (RBP4) is an adipocyte-derived hormone which contributes to pathogenesis of type 2 diabetes and had been shown to be elevated in insulin-resistance both in mouse models and humans." (PMID 28848425, 2017).
Insulin resistance (continued). "Moreover, RBP-4 (retinol binding protein-4) excessively expressed in abnormal adipose tissue, inhibits GLUT4 expression leading to insulin resistance." (PMID 29064461, 2017). "Adipokines, such as adiponectin, resistin, retinol-binding protein 4 (RBP4), are secreted by adipose tissues, which may play a critical role in systemic inflammation and insulin resistance (IR) in obesity and hypertension." (PMID 25878729, 2015). "Statistical analysis revealed that 25(OH)D had a negative correlation with RBP4, duration, HbA1c, homeostasis model assessment for insulin resistance (HOMA-IR), and fasting plasma glucose (FPG)." (PMID 25922846, 2015). "In conclusion, RBP4 correlates positively with serum RLP-TG independent of markers reflecting insulin resistance including visceral fat accumulation in patients with type 2 diabetes mellitus." (PMID 23671852, 2013). "In accordance with previous findings, we have confirmed that plasma RBP4 levels are elevated in obese subjects with MetS and T2D but do not correlate with insulin resistance, but rather with triglycerides." (PMID 24223837, 2013). "Several studies in humans have shown that RBP4 levels are positively correlated with those of triglycerides but not with insulin resistance." (PMID 24223837, 2013). "A correlation between insulin sensitivity and serum concentrations of RBP4 has, however, not been consistently reported, and a number of reports have questioned the role of RBP4 in insulin resistance." (PMID 23781325, 2013). "In healthy subjects, serum RBP4 levels were not affected by GH administration (mg/l): 41.7±4.1 (GH) vs 43.8±4.6 (saline), P=0.09, although GH induced insulin resistance." (PMID 23781325, 2013). "It has been described that plasma RBP4 is increased in subjects with obesity, impaired glucose tolerance, and diabetes mellitus, but other studies did not support the relation between RBP4 and insulin resistance." (PMID 21869928, 2012). "The exact relationship between WAT Rbp4 mRNA level, body weight, and insulin resistance is not clear." (PMID 20307313, 2010). "RBP4 serum levels did not correlate with adiponectin, resistin or ghrelin serum concentrations, nor did adiponectin, resistin or ghrelin correlate with insulin resistance (data not shown)." (PMID 20932285, 2010). "Accordingly, obesity and increased insulin resistance, in subjects with NAFLD, may contribute to elevation of the circulating RBP4 levels." (PMID 17941908, 2008). "Therefore, suppression of RBP4 may represent a key mechanism by which ATRA attenuates obesity-induced inflammation and insulin resistance." (PMID 41157128, 2025). "Moreover, serum RBP4 levels decreased in people in whom exercise improved insulin sensitivity, but not in those people in whom this effect was not achieved, indicating an RBP4-mediated link between a physically inactive lifestyle and insulin resistance." (PMID 38966226, 2024). "This increase was observed in adipose tissue rather than the liver, leading to the hypothesis that RBP4 acts as an adipokine that links obesity and insulin resistance." (PMID 38673873, 2024). "Two studies provided data on the relationship between insulin resistance and RBP4 levels, and three studies offered correlation coefficients for the relationship between aspartate aminotransferase (AST) and alanine aminotransferase (ALT) levels with RBP4 levels." (PMID 39589965, 2024). "Hence, there is a lack of reviews focused on investigating the effects of RBP4 on both insulin resistance and pancreatic β-cell function." (PMID 38520616, 2024). "Additionally, the common comorbidities of psoriasis include insulin resistance, obesity, and metabolic syndrome, in which RBP-4 has been found to be involved; hence, it is rather complicated to expound the specific actions of RBP-4 in psoriasis with current data." (PMID 37711744, 2023).
Insulin resistance (continued). "We speculate that besides insulin resistance, RBP4 may have additional unique non-renal function mechanisms such as pro-inflammatory effects and direct effects on vascular smooth muscle and uric acid." (PMID 35846279, 2022). "We studied the effects of IT protocol on RBP4, aHSG/fetuin-A, FGF21, and CRP levels, liver histology, HOMA-IR as well as total lipid content in the obese Zucker (Crl:ZUC(ORL)-Leprfa) rats—an animal model of insulin resistance, glucose intolerance, metabolic syndrome, and genetic obesity." (PMID 33833309, 2021). "Since RBP4 expression was increased in adipose tissue but not liver, these findings led to the hypothesis that RBP4 acts as an adipokine, linking obesity with insulin resistance." (PMID 33790810, 2021). "This RBP4-induced APC activation results in proinflammatory CD4+ T cell proliferation and Th1 polarization (Th1), which further orchestrates adipose tissue inflammation (mononuclear cell infiltration and proinflammatory cytokine production) and, therefore, insulin resistance." (PMID 25918733, 2015). "In addition, it has been shown that higher retinol-binding protein 4 (RBP4) and lower glucose transporter 4 (GLUT4) might contribute to an unfavorable metabolic condition including insulin resistance." (PMID 25935836, 2015). "It is therefore likely that hepatic rather than peripheral insulin resistance interacts with RBP4." (PMID 23781325, 2013). "The data suggest that liver RBP-4 might not correlate with insulin resistance, but more studies are required to generate a solid conclusion." (PMID 24367155, 2013). "RBP-4 concentrations in other tissues did not correlate with insulin resistance." (PMID 24367155, 2013). "However, a recent study reported a strong correlation between RBP4 and insulin resistance in nondiabetic subjects without a medical or family history of diabetes." (PMID 24282409, 2013). "Furthermore, some reports have shown that RBP4 correlates with hypertriglyceridemia independent of insulin resistance." (PMID 23671852, 2013). "Similarly, plasma concentrations of retinol binding protein 4 (RBP4), an adipokine involved in the development of insulin resistance, were not modified in HSL+/− and HSL inhibitor-treated mice compared to control mice." (PMID 23431266, 2013). "Interestingly, NT-proCNP in critically ill patients was indeed correlated with endogenous insulin levels (C-peptide) as well as serum resistin and retinol-binding protein 4, two mediators of insulin resistance (data not shown)." (PMID 21281508, 2011). "Moreover, long-term treatment with fenretinide for several months prevented high-fat diet induced obesity, insulin resistance, and hepatic steatosis, whereas, unexpectedly, some of these beneficial effects were also observed in mice lacking RBP4, proposing also RBP4-independent mechanisms at play." (PMID 33790810, 2021). "However, Rbp4 promotes insulin resistance and lack of Rbp4 improves glucose homeostasis." (PMID 27845741, 2016). "Thus, acute ghrelin infusion upregulates RBP4 gene expression in adipose tissue, but this does not translate into measurable alterations in circulating RBP4 concentrations, suggesting that RBP4 is not involved in ghrelin-induced insulin resistance." (PMID 23781325, 2013). "Therefore it has been speculated that adipocyte derived RBP4—not hepatic RBP4—may be an adipokine and contribute to the development insulin resistance." (PMID 22254074, 2011). "Although serum RBP4 levels were increased in younger women with PCOS compared with age-matched non-PCOS controls, RBP4 does not seem to be a good marker of insulin resistance or other metabolic derangements in women with PCOS." (PMID 31051472, 2019). "In fact, RBP4 has been shown to play a role in TLR4-mediated inflammatory signaling and insulin resistance independent of STRA6." (PMID 28689994, 2017).
Insulin resistance (continued). "RBP4 levels in the patients with impaired fasting glucose (IFG), insulin resistance or hyperinsulinemia were significantly higher than the patients without IFG, insulin resistance or hyperinsulinemia (P = 0.035, P = 0.001, and P = 0.007)." (PMID 31956345, 2020). "This perhaps suggests that ghrelin cell-derived RBP4 and TTR may not impact whole body insulin resistance and/or thyroid hormone transport." (PMID 23840311, 2013).